CALR (calreticulin)
Diseases named in the same sentence as CALR in open-access papers (continued):
Sharing a sentence is not in itself a finding about the gene and the disease.
Insulin resistance (4 papers, 2015 to 2024). Increased resistance towards insulin, that is, diminished effectiveness of insulin in reducing blood glucose levels. "Both PDIA3 and CALR were positively associated with insulin resistance, cholesterol, and triglycerides and the number of criteria identifying metabolic syndrome and negatively with fasting and post-challenge insulin sensitivity." (PMID 36213269, 2022). "Our preliminary data suggest that CALR and PDIA3, two key molecules of ER stress, could be related to insulin resistance and altered lipid profile in pediatric obesity." (PMID 36213269, 2022). "CALR and PDIA3 could be early markers of insulin resistance and dyslipidemia-related ER stress, being useful to stratify patients at high risk of further complications over time." (PMID 36213269, 2022). "CALR and PDIA3 could be early markers of insulin resistance and dyslipidemia-related ER stress useful to stratify patients at high risk of further complications." (PMID 36213269, 2022).
vitiligo (4 papers, 2021 to 2025). Generalized well circumscribed patches of leukoderma that are generally distributed over symmetric body locations and is due to autoimmune destruction of melanocytes. "The pathogenesis of endoplasmic reticulum stress in vitiligo remains to be elucidated, but it is speculated that Ca2+ interference and translocation of calreticulin (CRT) may be the main pathways leading to melanocyte death." (PMID 35321240, 2022). "Another candidate for sensing the immune system in vitiligo is calreticulin (CRT)." (PMID 33936032, 2021). "Calreticulin (CRT), a ubiquitous ER protein modulating intracellular Ca2+ homeostasis, is manifested to be positively related to lesional area and duration of vitiligo in patients." (PMID 33200838, 2021).
astrocytoma (3 papers, 2014 to 2019). "Interestingly, levels of both BiP and calreticulin were increased in iron-burdened astrocytoma cells, and BiP expression was increased in dietary iron-loaded mice." (PMID 30873154, 2019).
atherosclerosis (3 papers, 2021 to 2025). A disease characterized by the build-up of fatty material and calcium deposition in the arterial wall resulting in partial or complete occlusion of the arterial lumen. "Overall, this study provides comprehensive mechanistic insights into how macrophage P2Y6 receptor-mediated PLCβ/store-operated Ca2+ entry/calreticulin/SR-A signalling pathways contribute to atherosclerosis." (PMID 40072682, 2025). "A decrease in ABCA1-mediated reverse cholesterol efflux and impaired efferocytosis mediated by enhanced CD 47 expression over calreticulin can lead to progression of atherosclerosis lesions." (PMID 34944106, 2021). "This case illustrates how ET, particularly CALR-mutated subtypes, can manifest as acute coronary syndrome in the absence of atherosclerosis and underscores the need to consider hematologic malignancies in atypical presentations of myocardial infarction." (PMID 40278216, 2025). "Phagocytosis was restored upon silencing of cyclophilin A. New Zealand white rabbits were fed a high-fat diet, and lesions in their aortae were analyzed histologically for evidence of atherosclerosis and the expression of Cyp A, CD 47 and calreticulin, the ligand receptor involved in efferocytosis." (PMID 34944106, 2021).
bladder urothelial cancer (3 papers, 2019 to 2025). "Secretion of mutated CALR has also been observed in liquid biopsies samples as urine in bladder urothelial cancer patients." (PMID 38035116, 2023). "In bladder urothelial cancer, calreticulin in urine is a candidate biomarker." (PMID 30974841, 2019). "al., which contains CALR, IFNB1, and IFNG, showed a powerful function in bladder urothelial carcinoma prognosis and immune landscape determination." (PMID 40557150, 2025).
breast adenocarcinoma (3 papers, 2016 to 2020). "We found 48 h of cisplatin treatment enhanced calreticulin translocation and induced ER-stress of the murine breast adenocarcinoma E0771 cells and significantly increased BM-derived APC phagocytosis of the E0771 cells." (PMID 32198351, 2020).
colorectal tumours (3 papers, 2016 to 2024). "Meanwhile, porphyrin-lipid, as a photosensitizer, incorporated into zinc nanoparticles and polymeric core–shell nanoparticles, has been reported to induce apoptosis and necrosis, triggering upregulation of calreticulin expression in 4T1 breast and CT26 colorectal tumor cells, respectively." (PMID 36405502, 2021).
COVID-19 (3 papers, 2021 to 2025). A disease caused by infection with severe acute respiratory syndrome coronavirus 2. "This study provides new insight into the infectivity of SARS-CoV-2, calcium hemostasis, and the role of CALR in the ER-lysosome-dependent proteolysis of the spike protein, which could be associated with cardiovascular complications in COVID-19 patients." (PMID 38067122, 2023). "Specifically, along with CD68, the immunoproteasome-related genes PSMB8, TAP1, PSMB9, PSMB10, and calreticulin (CALR) were all found to be expressed in the CD14+/CD16+ subpopulation of cells during mild COVID-19." (PMID 34225749, 2021). "Our cell trajectory also highlighted a difference in the activation of calreticulin in equivalent cell populations in mild versus severe cases of COVID-19, with the latter demonstrating relative impairment." (PMID 34225749, 2021). "Similarly, in the trajectory signature for alveolar macrophages from mild COVID-19 patients, CALR, MARCO and TNFSF13 followed the expression patterns of CD68 and PSMB8." (PMID 34225749, 2021). "However, a link between the severity of COVID-19 and CALR mutations has not been established and requires further investigation." (PMID 38067122, 2023).
endometrial cancer (3 papers, 2020 to 2024). Primary or metastatic malignant neoplasm involving the endometrium (mucous membrane that lines the endometrial cavity). "Overexpression of calreticulin was reported to be associated with longer survival in endometrial cancer patients." (PMID 35454982, 2022). "Xu and colleagues reported that low CALR expression was significantly associated with endometrial cancer progression and poor prognosis." (PMID 33221760, 2020). "Calreticulin was found upregulated in the endometrial cancer tissues of the diabetic group." (PMID 35454982, 2022).
mesothelioma (3 papers, 2018 to 2023). A usually malignant and aggressive neoplasm of the mesothelium which is often associated with exposure to asbestos. "We evaluated the ability of SS1P to induce adenosine triphosphate (ATP) secretion and calreticulin expression on the surface of AE17M mouse mesothelioma cells." (PMID 30441807, 2018).
metastatic tumors (3 papers, 2019 to 2025). "Silencing ADAR1 significantly reduced the volume of peritoneal metastatic tumors and weakened oncogene CALR expression, Wnt / β-catenin pathway and epithelial-mesenchymal transition (EMT) process in vivo." (PMID 35003354, 2021). "Immunofluorescence was presented for evaluating the expression of ADAR1, CALR, E-cadherin, Vimentin, and β-catenin proteins in peritoneal metastatic tumor tissues." (PMID 35003354, 2021). "Furthermore, lowered CALR expression was detected in peritoneal metastatic tumors following treatment with si-ADAR1." (PMID 35003354, 2021). "Importantly, CALR levels in both PT and metastatic tumors (MT) were significantly associated with improved RFS and OS (median RFS PT: 43 mo." (PMID 31747968, 2019).
osteoarthritis (3 papers, 2021 to 2022). A noninflammatory degenerative joint disease occurring chiefly in older persons, characterized by degeneration of the articular cartilage, hypertrophy of bone at the margins and changes in the synovial membrane. "Due to these alterations, it could be thought that “eat-me” signals, such as calreticulin, may be altered in SC associated with pathological processes during aging such as osteoarthritis, Alzheimer’s and Parkinson’s diseases, and cancer." (PMID 34638556, 2021).
renal carcinoma (3 papers, 2020 to 2024). A carcinoma arising from the epithelium of the renal parenchyma or the renal pelvis. "Renal cancer patients with higher CALR expression show a lower 5-year survival rate (44% vs. 76%) compared to those with lower CALR expression." (PMID 33221760, 2020).
schizophrenia (3 papers, 2015 to 2019). A major psychotic disorder characterized by abnormalities in the perception or expression of reality. "Our results showed consistent downregulation of both N-glycan and calnexin/calreticulin pathways in shared genetic risk and an actual illness, implying their essential role in schizophrenia." (PMID 31477693, 2019). "Unusual manifestations of calreticulin have been observed in various cancers occurred in ovary, pancreas, and breast and point mutations in the CALR gene promoter have been reported in patients with schizophrenia." (PMID 27486987, 2016).
thyroid cancer (3 papers, 2020 to 2022). "However, in thyroid carcinoma (THCA), the expression of CALR decreased and there was no significant change of expression in the other five tumors, which may be related to different carcinogenic mechanisms in different tumors." (PMID 34910788, 2021).
acute lung injury (2 papers, 2020 to 2021). A condition of lung damage that is characterized by bilateral pulmonary infiltrates (pulmonary edema) rich in neutrophils, and in the absence of clinical heart failure. "However, whether CALR affects macrophages and modulates progression of acute respiratory distress syndrome/acute lung injury (ARDS/ALI) remains unknown." (PMID 32082309, 2020).
Babesia infection (2 papers, 2017 to 2022). "In this study, calreticulin immunolocalization assays have shown that this molecule can be found in the tick midgut, ovaries and SGs, suggesting that it might have a role in Babesia infection in all these tissues." (PMID 29034218, 2017). "According to this and to other reports, it is thought that calreticulin acts during blood feeding and may alter calcium metabolism during Babesia infection." (PMID 29034218, 2017).
blood disease (2 papers, 2021 to 2023). A disease that occurs in the blood. "Despite the limitations of C. elegans as a model to recapitulate a blood disease, according to the results shown here, this organism seems to be a potential model for the analysis of some of the aberrant mechanisms triggered by mutant calreticulin." (PMID 36611979, 2023). "Consequently, our results discussed the connections between the hub genes EPB42, CALR, SLC4A1, MPL and PMF together with other related blood diseases comprehensively." (PMID 34633991, 2021).
brain tumors (2 papers, 2019). "Interestingly, vorinostat induced the exposure of calreticulin (CALR) on the surface of childhood brain tumors." (PMID 31805711, 2019).
breast ductal adenocarcinoma (2 papers, 2016 to 2021). A breast carcinoma arising from the ducts. "It has been reported that compared with normal tissues, the expression level of CALR in colorectal cancer vaginal cancer, oral cancer, breast ductal carcinoma and PRAD was increased." (PMID 34910788, 2021). "A higher expression of calreticulin protein in breast ductal adenocarcinomas has been previously reported, which possibly indicates to a correlation between the presence of calreticulin and the initiation and/or progression of cancer." (PMID 27418879, 2016). "In brief, the tumor-promoting effects of calreticulin or its overexpression has been reported in ductal carcinoma of the breast, bladder cancer, and prostatic adenocarcinoma." (PMID 27418879, 2016).
breast tumor (2 papers, 2016 to 2018). "This is in concordance with previous studies in which calreticulin overexpression was described in breast tumor epithelial cells, in which a correlation between calreticulin overexpression and the development of post-operative distant metastasis were reported." (PMID 27418879, 2016).
colitis (2 papers, 2021 to 2022). Inflammation of the colon. "Calreticulin (CALR), which appears to play a role in leukocyte infiltration in mouse models of colitis via its interaction with alpha integrins, was down-regulated in S89A mice (~30%)." (PMID 33799418, 2021).
colon adenocarcinoma (2 papers, 2021). "While in colon adenocarcinoma (COAD) and THCA, down-regulated CALR is associated with the higher tumor stage." (PMID 34910788, 2021).
cytomegalovirus infection (2 papers, 2022 to 2023). A herpesvirus infection caused by Cytomegalovirus. "Another protein of interest is calreticulin, which is known to be released onto the cell surface as an eat-me signal as a result of infection, such as in Mycobacterium tuberculosis and cytomegalovirus infections." (PMID 38098491, 2023). "Several of the PM proteins that were strongly upregulated during VACV infection were also upregulated at the cell surface during HCMV infection, including HSPA5, CALR and ERAP1." (PMID 35727847, 2022).
dyslipidemia (2 papers, 2018 to 2022). "This was also confirmed by the direct association of CALR and PDIA3 with the number of metabolic alterations typical of metabolic syndrome." (PMID 36213269, 2022).
fibrosarcoma (2 papers, 2019 to 2020). A malignant mesenchymal fibroblastic neoplasm affecting the soft tissue and bone. "DACT also stimulated all ICD hallmarks (eIF2α phosphorylation, CALR exposure, ATP and HMGB1 release, as well as induction of type 1 interferon‐related metagene) in another cell line, the murine methylcholanthrene‐induced fibrosarcoma MCA205 (Fig EV1)." (PMID 32323922, 2020).
fibrosis (2 papers, 2016 to 2023). the formation of excess fibrous connective tissue in an organ or tissue in a reparative or reactive process. "The role of CALR in fibrosis is complex as in early classic experiments using inductive models of organ‐specific fibrosis, CALR was shown to be upregulated in animal fibrosis models of rat renal tubules and lung but not in a cardiac model." (PMID 37985392, 2023).
GNE myopathy (2 papers, 2013 to 2014). "Strikingly, calreticulin was found to be highly expressed in GNE myopathy, a distal myopathy associated with rimmed vacuoles." (PMID 25353622, 2014). "Immunofluorescence study showed that calnexin (Fig. 1b1), calreticulin (Fig. 1b3), GRP94 (Fig. 1c1), GRP78 (Fig. 1d1) were expressed in the muscle tissues of GNE myopathy patients whereas, normal control exhibited no immunoreactivity for these molecules (Fig. 1b2, b4, c2, and d2)." (PMID 23472144, 2013).
hypercoagulability (2 papers, 2020 to 2023). "Patients with JAK2V617F had a higher phosphatidylserine exposure than CALR and triple-negative groups, which was correlated with more hypercoagulability and could possibly explain the higher thrombotic risk in the JAK2V617F group." (PMID 36908768, 2023). "Finally, JAK2 and CALR mutations were not performed in all patients as these tests were later included in the thrombophilia workup." (PMID 32878264, 2020).
idiopathic inflammatory myopathy (2 papers, 2020 to 2023). Idiopathic form of inflammatory myopathy. "Anti-calreticulin autoantibodies were reported in a cohort of idiopathic inflammatory myopathy patients and associated with malignancy." (PMID 37767091, 2023).
laryngeal carcinoma (2 papers, 2014 to 2018). Carcinoma that arises from the laryngeal epithelium. "For example, Apo-AI only showed differential expression in N+ lymph nodes of floor of the mouth tumors, and calreticulin and PDI in N+ lymph nodes of larynx carcinomas." (PMID 30157864, 2018).
liver cancer (2 papers, 2015 to 2026). An epithelial or non-epithelial malignant neoplasm that arises from the liver. "Taken together, these observations suggest that CALR enhances the carcinogenic function via ARAF in liver cancer." (PMID 41262532, 2026). "To address the effect of CALR on liver cancer cells, we cloned the CALR into the lentiviral vector pLVX-ZsGreen-Puro (pLVX-CALR) and prepared rLV-CALR lentivirus." (PMID 41262532, 2026). "In conclusion, we clearly demonstrate that CALR accelerates the growth of liver cancer cells by enhancing ARAF expression and telomere function (Fig. 1Z3)." (PMID 41262532, 2026). "In this study, we demonstrate that CALR accelerates the growth of liver cancer cells by enhancing telomere activity dependent on ARAF (A-Raf proto-oncogene, serine/threonine kinase)." (PMID 41262532, 2026). "Importantly, single-cell RNA sequencing showed that CALR affected the heterogeneity of liver cancer and its microenvironment network, involving ARAF." (PMID 41262532, 2026). "Taken together, these observations suggest that CALR alters gene expression and the telomerase activity dependent on ARAF in liver cancer." (PMID 41262532, 2026). "Moreover, RNA sequencing and protein sequencing indicate that CALR could affect gene expression (e.g., ARAF) by altering transcriptome and proteome in human liver cancer cells." (PMID 41262532, 2026).
lung fibrosis (2 papers, 2018 to 2025). "CALR was also upregulated in a bleomycin-induced animal model of lung fibrosis." (PMID 29214350, 2018). "At the same time, calreticulin was not related to cardiac fibrosis in the animal model, although it was upregulated in the animal model of lung fibrosis." (PMID 40564271, 2025).
mantle cell lymphoma (2 papers, 2022 to 2025). Mantle cell lymphoma is a rare form of malignant non-Hodgkin lymphoma affecting B lymphocytes in the lymph nodes in a region called the ``mantle zone''. "To note, high CRT gene (CALR) transcription has been correlated with rapid tumor progression and poor prognosis of patients affected by gastric malignancy, Non-Small Cell Lung Cancer (NSCLC), breast carcinoma, neuroblastoma, pancreatic cancer, bladder carcinoma, and mantle cell lymphoma." (PMID 39857785, 2025).
myelogenous leukemia (2 papers, 2015 to 2025). "In our present study, several calcium-binding proteins were identified in doxorubicin-resistant myelogenous leukemia cells, such as sorcin, protein S100-A4, annexin A4, calreticulin, etc., indicating that metal ions such as calcium might play a pivotal role in the development of chemoresistance." (PMID 25628518, 2015).
Myocardial fibrosis (2 papers, 2024 to 2025). "Fibroblasts presenting increased calreticulin expression show higher viability and invasiveness and decreased apoptosis, suggesting a potential role of calreticulin in myocardial fibrosis." (PMID 40564271, 2025).
myocardial infarction (2 papers, 2023 to 2025). Gross necrosis of the myocardium, as a result of interruption of the blood supply to the area, as in coronary thrombosis. "Previous case reports have noted myocardial infarction as the initial manifestation of ET, yet CALR-mutated cases remain rarely described." (PMID 40278216, 2025).
oral cancer (2 papers, 2019 to 2021). "It was also been reported that stable knockdown of CALR in oral cancer cells reduced cell proliferation." (PMID 34580365, 2021). "In oral cancer cells, depletion of calreticulin was found to result in cell cycle arrest at the G0/G1 phase, suppressing growth rates, colony-formation capacity, and anchorage-independent growth." (PMID 30974841, 2019).
pancreatitis (2 papers, 2016 to 2019). Inflammation of the pancreas. "EGFR mRNA expression did not change with the onset of pancreatitis, but EGFR protein translocated from the endoplasmic reticulum to the plasma membrane in acinar cells as indicated by its enhanced co-localization with E-cadherin instead of calreticulin." (PMID 27764193, 2016).
Parkinson disease (2 papers, 2021 to 2025). A progressive degenerative disorder of the central nervous system characterized by loss of dopamine producing neurons in the substantia nigra and the presence of Lewy bodies in the substantia nigra and locus coeruleus. "The hub genes connecting these processes included parkinsonism‐associated deglycase (Park7), peroxiredoxin 6 (Prdx6), Jun proto‐oncogene (Jun), and calreticulin." (PMID 41164797, 2025).